IL6 (interleukin 6)
Diseases named in the same sentence as IL6 in open-access papers (continued):
Sharing a sentence is not in itself a finding about the gene and the disease.
lymph node metastasis (continued). "Median plasma levels of IL6 and IL6sR were significantly higher among patients with adverse pathologic features such as lymphovascular invasion, lymph node metastasis and advanced pathologic tumor stage (p-values < 0.05)." (PMID 34023914, 2022). "Overall, IL-6 has been described to be upregulated in advanced BlCa patients and in lymph node metastasis." (PMID 36699696, 2022). "Our results revealed significant differences in lymph node metastasis and serum concentrations of IL-6 as well as SAA." (PMID 36316846, 2022). "The results indicated that lymph node metastasis and TNM staging are both independent risk factors connected to IL-6 and IL-12P7; the degree of differentiation being an independent risk factor (P <0.01) connected with TNF-α level (P <0.01)." (PMID 36226059, 2022). "In CRC, IL-6 plays a significant clinical pathological role, as IL-6 is positively correlated with tumor TNM stage and associated with invasion depth and lymph node metastasis." (PMID 34572947, 2021). "The IL-6, as well as the sCD40L concentrations, reached the highest values in the group of patients only with lymph node metastases." (PMID 34441316, 2021). "IL-1β, IL-6 and IL-10 immunostaining was significantly higher in tumour and lymph node metastasis than in MSR squamous epithelium (p<0.001)." (PMID 31870104, 2019). "A study was considered to evaluate the correlation between IL-6 and clinical characteristics in GI cancer if a test was performed for cancer specific findings such as lymph node metastases, invasion, distant metastases or tumor size." (PMID 30038723, 2018). "Patients with advanced/metastatic cancer had high IL-6, and IL-6 expression was significantly elevated in CRC tissues compared to noncancerous tissues and was associated with invasiveness and lymph node metastasis." (PMID 29546074, 2018). "The results of the recently published Chinese study suggest that IL-6 expression in the CRC tissue is associated with tumor TNM stage, invasion depth, and lymph node metastasis in CRC." (PMID 30154846, 2018). "Age, CA 19-9, Karnofsky performance status, lymph nodes metastasis, peritoneum metastasis, SNP rs11212617, adiponectin, IL-6." (PMID 28903435, 2017). "The destruction of nearby tissue and lymph node metastasis is generally accompanied by tissue inflammation, and the infiltration of inflammatory cells and the production of cytokines, especially IL-6, increase the CRP level in the serum." (PMID 23383155, 2013). "Another retrospective analysis investigated the correlation of c-met, cox2, and IL6 expression with invasiveness and lymph node metastasis in a series of 114 patients." (PMID 20003448, 2009). "The group of patients with lymph node metastases or bone metastases had similar IL-6 and TNF-α levels (P=0.31 and P=0.28), which were higher than those in the group with localised disease (P<0.001)." (PMID 15150588, 2004). "UBC cases with lymph node metastases have higher serum levels of IL-6 than do cases with low IL-6." (PMID 40149682, 2025). "Indeed, patients with lymph node metastases and normal IL-6 production had a good prognosis, whereas patients with such metastases and an enhanced production of IL-6 were found to have progressive disease." (PMID 39518029, 2024). "Also, enhanced IL-6 expression was positively correlated with lymph node metastasis, tumor differentiation, and vascular invasion in PC patients." (PMID 38715108, 2024). "However, IL-6 expression was related to OS, and unrelated to lymph node metastasis, tumor size, histological grade or DFS in patients with breast cancer." (PMID 36693957, 2023). "In addition, serum levels of both proteins tested varied according to nodal metastases, and the SAA and IL-6 concentrations were correlated with the presence of lymph node metastasis." (PMID 36316846, 2022). "In addition, IL-6 and IL-12P7 are associated with TNM staging and lymph node metastasis, while TNF-α is related to differentiation." (PMID 36226059, 2022).
lymph node metastasis (continued). "In addition, we observed that Cluster of differentiation 40 (CD40, p = 0.017), C–C motif chemokine 16 (CCL16, p = 0.019) and IL-6 (p = 0.021) were highly secreted from PDS MCF7-cultures from patients with lymph node metastasis." (PMID 34090457, 2021). "IL-6 level showed a negative association with relapse-free survival of patients with lymph node metastasis or grade 3 tumors." (PMID 31252615, 2019). "Patients with lymph node metastasis, deeper tumor infiltration depth, and higher TNM stage have higher expression levels of IL-6 in the serum." (PMID 40606986, 2025). "Elevated serum and tissue levels of IL-6 have been consistently reported in patients with OSCC, particularly in advanced stages and in cases with lymph node metastases." (PMID 40944094, 2025). "Porphyromonas intermedia infection promoted growth of SCC-7 cells injected into the buccal submucosa, leading to angiogenesis, muscle invasion, lymph node metastasis, and elevated expression of Ki-67, VEGF-A, IL-6, IL-17, and ISG15." (PMID 40924302, 2025). "Earlier data also showed that the PDS induction of IL-6 secretion in MCF7 cells correlated with high tumor grade (p = 0.004) and patients with lymph node metastasis (p = 0.021), supporting the relevance for a link to more aggressive cancer features." (PMID 38136303, 2023). "The expressions of IL-6, STAT3, p-STAT3, JAK2, p-JAK2 and CyclinD1 in NPC tissues were higher and correlated with TNM stage and lymph node metastasis (LNM)." (PMID 34165442, 2021). "For IL-6, a positive correlation was found with lymph node metastasis and correspondingly a negative correlation with survival of patients with GC." (PMID 36976399, 2023). "Multi-factor analysis of IL-6, TNF-α and IL-12P7 levels in patients refers to three factors (lymph node metastasis, historical score and TNM staging) as the argument, which uses the expression of IL-6, TNF-α and IL-12P7 as the dependent variable by multi-step regression analysis." (PMID 36226059, 2022). "In the case of lymph node metastasis and distant metastasis, as well as the grading of histological malignancy, our study showed no statistical differences in the methylation status of the IL-6 promoter between analysed subgroups." (PMID 37047238, 2023). "Furthermore, the IL-6 rs1800796 heterozygous genotype and the absence of distant metastases were significantly related, whereas the mutant and recessive model were significantly related to lymph node metastasis." (PMID 34150619, 2021).
non-alcoholic steatohepatitis (59 papers, 2009 to 2025). "Similarly, elevated levels of interleukin-6 showed a notable correlation with plasma Cers and have been linked to the severity of non-alcoholic steatohepatitis." (PMID 38561799, 2024). "Additionally, Tyr lowers the expression of prooxidant enzyme NOX1 as well as the mRNA expressions of transforming growth factor β1 (TGF-β1) and IL-6, reducing inflammation associated with non-alcoholic steatohepatitis (NASH) and showing protective effects against liver immune infiltration." (PMID 40298838, 2025). "Data suggest that in chronic inflammatory states, elevated IL-6 correlates with increased hepatocyte IL-6 expression and development of nonalcoholic steatohepatitis." (PMID 40646134, 2025). "Inflammation, mediated by TNF-α and IL-6, promotes non-alcoholic steatohepatitis (NASH) through macrophage infiltration and Kupffer cell activation, leading to hepatic fibrosis and cirrhosis." (PMID 41235339, 2025). "Xiang reported that kaempferol down-regulated the mRNA expression of TNF-α and IL-6 in a murine model of non-alcoholic steatohepatitis induced by a high-fat diet and exhibited excellent antioxidant and anti-inflammatory activities." (PMID 38630770, 2024). "Another study elucidated the role of the inflammatory cytokine IL-6 in the pathogenesis of non-alcoholic steatohepatitis, a prevalent liver disease with poorly understood inflammatory mechanisms." (PMID 38535313, 2024). "Another proinflammatory cytokine is IL-6, for which there are indicative studies that suggest its ability to detect inflammation-related nonalcoholic steatohepatitis." (PMID 37999211, 2023). "The expression levels of pro-inflammatory cytokines, including tumor necrosis factor-α (TNF-α), IL-6, and IL-1β, were significantly decreased in the non-alcoholic steatohepatitis by inhibiting ferroptosis." (PMID 37970439, 2023). "Blood levels of IL-6 were increased in accordance with the histological severity of non-alcoholic steatohepatitis." (PMID 36564799, 2022). "IL-6 promotes macrophages-derived miR-223-enriched exosomes to suppress the several miR-223-targeted genes expressed in hepatocytes in a nonalcoholic steatohepatitis (NASH) model." (PMID 35087870, 2021). "SLBZS treatment inhibited the TLR4/p38 MAPK signaling pathway, attenuating lipid metabolic disturbance, reducing IL-1β, TNF-α, and IL-6 levels, and reversing non-alcoholic steatohepatitis progression." (PMID 32460745, 2020). "Similar, the modification of cytokines including plasminogen activator inhibitor 1, adiponectin or interleukin 6, have been described in the association with NAFLD, and more strongly with non-alcoholic steatohepatitis." (PMID 29895299, 2018). "PTGS2 (degree = 14) amplifies inflammatory cascades by converting FASN-derived arachidonic acid into protumorigenic prostaglandin E2, establishing a self-perpetuating lipid-inflammation feedforward loop that drives IL-6/STAT3-mediated malignant transformation in non-alcoholic steatohepatitis." (PMID 40839202, 2025). "Moreover, in male rats with liver steatosis, androgens have been demonstrated to reduce the risk of a progression to non-alcoholic steatohepatitis (NASH) by downregulating the proinflammatory cytokines TNF-α and IL-6." (PMID 36142565, 2022). "Wieckowska and coworkers demonstrated a markedly increased hepatic IL-6 expression assayed with immunohistochemistry in patients with non-alcoholic steatohepatitis, as compared to normal liver, and found hepatic IL-6 expression to be correlated with the severity of inflammation and fibrosis." (PMID 26927057, 2016). "In animal models with nonalcoholic steatohepatitis (NASH), the administration of FGF21 analogues was associated with reduced expression of several proinflammatory cytokines, including tumor necrosis factor a (TNF-a), interleukin-6 (IL-6), IL-1, and interferon-γ (IFN-γ)." (PMID 35200696, 2022).
non-alcoholic steatohepatitis (continued). "In non-alcoholic steatohepatitis (NASH) mice, quercetin and its glycoside rutin were shown to reduce TNF-α and IL-6 inflammatory markers." (PMID 38225555, 2024). "In a mouse model of non-alcoholic steatohepatitis (NASH), knockout of IL-6 or IL-6R also reduced the signs of inflammation during NASH progression." (PMID 38890694, 2024). "In a murine model of non-alcoholic steatohepatitis, INT-767 significantly reduced pro-inflammatory cytokines production by macrophages such as IL-6 and TNF-a while increasing the anti-inflammatory cytokine IL-10." (PMID 37834329, 2023). "IL-1β, IL-6, and TNF-α were measured because these cytokines have demonstrated roles as mediators of injury in both alcoholic and nonalcoholic steatohepatitis, and PPAR agonists function in part by regulating proinflammatory responses." (PMID 26339530, 2012). "With regard to the cytokines, we focused on measuring IL-1β, IL-6, and TNF-α because these have been deemed the most relevant overall to the pathogenesis of alcoholic and non-alcoholic steatohepatitis." (PMID 26339530, 2012). "In mouse models of non-alcoholic fatty liver disease and its inflammatory progression to non-alcoholic steatohepatitis (NASH), treatment with either compound reduced hepatic steatosis, lowered pro-inflammatory cytokine levels (TNF-α, IL-6), and improved insulin sensitivity and glucose tolerance." (PMID 40565591, 2025). "KEGG enrichment analysis revealed an enrichment of the NAFLD pathway, suggesting that SLXG may potentially treat nonalcoholic steatohepatitis (NASH) by regulating the expression of genes such as CXCL8, AKT1, SREBF1, IL6, PPARA, and ADIPOQ." (PMID 39928768, 2025). "A previous study from our group indicated that BX795, a TBK1 inhibitor, suppressed the expression of inflammatory cytokines, such as IL-6 and IL-10, in a nonalcoholic steatohepatitis mouse model; however, the relevant mechanism was not defined." (PMID 34858401, 2021). "Moreover, it has been reported that hepatic ferroptosis plays an important role as the trigger for initiating inflammation in non-alcoholic steatohepatitis, showing that the expressions of TNF-α, IL-6, and IL-1β were significantly upregulated following ferroptosis." (PMID 37425328, 2023). "In a study in a non-alcoholic steatohepatitis mouse model, the hot water extract of C. longa inhibited the hepatic production of TNF-α, IL-1β, and IL-6, and in our earlier clinical studies, C. longa extract improved systemic inflammatory markers, including hsCRP, TNF-α, and IL-6." (PMID 36145139, 2022). "Serum tests such as interleukin-6 levels potentially could be used in the future to confirm the absence of nonalcoholic steatohepatitis (NASH)." (PMID 34441377, 2021). "Furthermore, it has been demonstrated that the plasma levels of these two inflammatory cytokines are increased in subjects with NAFLD and nonalcoholic steatohepatitis (NASH), whereas peripheral blood monocyte productions of TNF-α and IL-6 are increased in subjects with NASH." (PMID 28836404, 2017). "Individual studies and pilot trials of pentoxifylline in nonalcoholic steatohepatitis have suggested that anti-inflammatory therapy had effectively biochemical improvement and cytokine-mediated systemic inflammation amelioration (i.e., reduced plasma TNF-α and IL-6 levels)." (PMID 21477300, 2011). "IL-6 expression also correlates with disease severity in non-alcoholic fatty liver disease (NAFLD) and is higher in nonalcoholic steatohepatitis (NASH) than steatosis alone." (PMID 22514624, 2012).
Erythema (57 papers, 2013 to 2026). Redness of the skin, caused by hyperemia of the capillaries in the lower layers of the skin. "From a clinical perspective, the IL‐6 upregulation observed following Vistabex treatment warrants careful consideration, as IL‐6 is a pivotal cytokine in inflammatory processes, associated with edema, erythema, and increased skin rigidity." (PMID 41482677, 2026). "Macrophages release proinflammatory cytokines such as TNF-α, interleukin-1 (IL-1), and interleukin-6 (IL-6) leading to erythema and induration of the inoculation site caused by vasodilation, vascular permeability, and infiltration by immune cells." (PMID 35170334, 2022). "IL-6 deficient mice show reduced skin inflammation after intradermal injection of IL-23, which is a strong trigger of erythema and inflammatory infiltrates of the skin." (PMID 26999594, 2016). "The main observation indicators included patient's skin recovery-related indicators (time to erythema disappearance and time to scab shedding) and levels of inflammatory factors [serum interleukin-6 (IL-6) and tumor necrosis factor alpha (TNF-α)]." (PMID 42164155, 2026). "Previous studies have reported that MAPK activation triggers NF-κB, a key transcription factor that promotes the production of inflammatory cytokines, such as IL-6 and IL-8, thereby contributing to inflammatory responses characterized by erythema and itching." (PMID 40573205, 2025). "The suppression of TNF-α and IL-6 in CO2 treatments correlates with clinical observations of decreased erythema, reduced swelling, and improved granulation tissue formation." (PMID 39857811, 2025). "Myr treatment significantly alleviated IMQ-induced erythema, scaling, and epidermal thickening, improved skin-barrier function, and reduced the expression of IL-6, IL-17A, and TNF-α." (PMID 41471291, 2025). "Injection of IL-6 results in erythema and an infiltration of lymphocytes in the dermis, which is indicative of inflammatory changes as the result of high levels of IL-6." (PMID 36672184, 2023). "Compared to their wild-type counterparts, Keap1-knockdown mice have lower expression of the pro-inflammatory cytokines IL-6 and IL-1β and display reduced cutaneous erythema following acute exposure to solar-simulated UVR." (PMID 35753587, 2022). "This includes the NFκB transcription system upon which induction by UV leads to an increase in the level of various inflammatory cytokines, including IL-6 and TNFα that enhance inflammatory responses such as erythema and sunburn." (PMID 33808148, 2021). "Topical application of S. epidermidis or glycerol alone on ICR mice dorsal skin exposed to UVB showed noticeable erythema, ulceration, epidermal hyperplasia, and increased IL-6 levels." (PMID 31514281, 2019). "The erythema, barrier function, and epidermal thickness of the AD-like wounds were improved by CoQ0 through the reduction of IL-1β, IL-4, IL-6, IL-10, interferon (IFN)-γ, and by neutrophil infiltration in the lesional skin." (PMID 31849685, 2019). "Fisetin inhibits the UVB-induced expression of MMPs, COX-2, IL-6, and NF-κB, thus protecting the skin from wrinkles and erythema." (PMID 28994699, 2017). "Our results showed that UV exposure induced erythema, edema, and epidermal hyperplasia of the mice skin, while upregulating the levels of IL-1β, IL-6, TNF-α, and IL-10 in mice skin significantly." (PMID 26903706, 2016). "We found that the FSM diet prevented the increase in erythema intensity, epidermal thickness, CPDs, and 6-4PPs in the dorsal skin and in the IL-6 concentration in serum induced by UVB irradiation." (PMID 27556484, 2016).